TWIST1 (twist family bHLH transcription factor 1)
Diseases named in the same sentence as TWIST1 in open-access papers (continued):
Sharing a sentence is not in itself a finding about the gene and the disease.
cancer (continued). "Both in vitro and in vivo studies of our investigation revealed that knockdown of TWIST1 are associated with the inhibition of migration and invasion of cancer cells." (PMID 26023736, 2015). "Although these three histone H3-methyaltion patterns are linked to CGI methylation as well, the transcriptional regulatory mechanisms for Twist1 underlying histone modification are poorly understood in cancer cells." (PMID 26695186, 2015). "In human cancers, ectopic Twist1 expression is reported to be associated with malignant progression, invasion, epithelial-to-mechencymal transition, metastasis and stemness, indicating potential oncogenic functions of Twist1." (PMID 26695186, 2015). "Although DNA methylation of the Twist1 gene has been reported in cancer cells, the mechanisms underlying transcriptional activation remain uncertain." (PMID 26695186, 2015). "Specifically, we demonstrate that three of the MICB-targeting microRNAs: miR-20a, miR-17-5p and miR-93, also target the same site in the 3′UTR of TWIST1, a transcription factor implicated in cancer metastasis." (PMID 25426550, 2014). "Consistent with known Twist1 functions during development and in cancer cells, Twist1-DNA binding regions associated with genes related to cell migration and adhesion were detected in all three tissues." (PMID 25262113, 2014). "TWIST1 encodes for the TWIST-related protein 1, a transcription factor, which acts as an oncogene in several cancers and has been shown to be involved in the development of resistance towards chemotherapeutic drugs and evading apoptosis." (PMID 24887580, 2014). "Genetic alteration and morphological changes are modulated during cancer metastasis, such as loss of epithelial cell identity (e.g., occludin and EpCAM) and acquisition of mesenchymal features (e.g., vimentin and TWIST1)." (PMID 24039787, 2013). "Upregulation of Twist1 was associated with cellular resistance to microtubule-targeting anticancer drugs in various types of cancers." (PMID 22245869, 2012). "Additional studies are required to define the mechanisms by which Twist1 accelerates KrasG12D-induced lung tumors, as well as explain why different tissues exhibit differing cancer susceptibilities despite harboring the same initiating oncogenic event." (PMID 22654667, 2012). "The Twist1 gene encodes for an essential transcription factor required for embryogenesis and overexpressed in many cancer types." (PMID 22654667, 2012). "The association of TWIST1 with stemness and the fibroblast phenotype even in select adult tissues has led to its implication in diseases outside of the context of either development or cancer, particularly fibrosis." (PMID 38139368, 2023). "PRRX1 has been also implicated in a positive feed-back loop in which TWIST1 directly increased PRRX1 which subsequently induced Tenascin-C that itself stimulated TWIST1 activity in Cancer associated fibroblast (CAF), and in dermal and fetal Human lung fibroblast lines." (PMID 37261432, 2023). "As one of important EMT‐TFs, Twist1 has long been associated with cancer progression." (PMID 35601657, 2022). "Importantly, FGF1 expression was positively associated with ZEB1 and TWIST1 expression in pan-cancers." (PMID 35864158, 2022). "Additionally, cell lines transfected with TWIST1 acquired characteristics of activated cancer-associated fibroblasts." (PMID 35565409, 2022). "In addition, some reports indicated that TWIST1 is associated with angiogenesis and stemness in various cancers." (PMID 33752711, 2021). "In addition, ADQ reduced the expression of mesenchymal markers of cancer cells, which was associated with the suppressed expression of Twist1." (PMID 34408201, 2021).
cancer (continued). "Not only has elevated TWIST1 been associated with poorer survival in several cancers, including head and neck, but TWIST1 protein attenuates the response to chemotherapeutic drugs, which provides a rationale for the worse clinical outcomes in high TWIST1 expression patients." (PMID 33298572, 2020). "Furthermore, MYC and TWIST1 cause metastasis by switching a transcriptional program in cancer cells that induces cytokines." (PMID 33081056, 2020). "We next investigated whether high expression of Twist1 could be a prognostic marker of PCa due to its association with the metastasis of various cancers." (PMID 31383001, 2019). "However, we admit that hypermethylation of TWIST1 is associated with different types of cancer: breast, uterine cervix, ovary, bladder, gastric, lung, bone, pancreas, and brain." (PMID 29682198, 2018). "Furthermore, TWIST1 has been implicated in number of pro-progression phenotypes in cancers, including angiogenesis, increased cancer cell stemness, and cell survival signaling." (PMID 28283022, 2017). "Given its importance in mediating not only protein-protein interactions, but also the DNA binding activity of TWIST1, we hypothesize that the WR domain is a potential target to block TWIST1 functions associated with cancer." (PMID 28283022, 2017). "TTP expression has been reported to be inhibited in a variety of human cancer cells, which may cause a high level of Twist1 and Snail1 to be expressed in cancer cells." (PMID 26840564, 2016). "Notably, TWIST1, a critical inducer of epithelial–mesenchymal transition, which underlies the metastasis of carcinomas, was highly expressed in association with R882 mutations." (PMID 27724883, 2016). "This promoter methylation of TWIST1 by TQ is most likely cancer cell-specific, and might be associated with TWIST1 down-regulation." (PMID 26023736, 2015). "Thus, we report that TQ consistently reduced the expression of TWIST1, which is associated with cancer cell migration and invasion." (PMID 26023736, 2015). "All these results strongly support the critical role of TWIST1 maintaining the delicate balance during the inflammatory response and, furthermore, its importance in pathologic conditions associated with deregulation of inflammation, such as cancer." (PMID 25238494, 2014). "A recent study indicated that TWIST1 expression is associated with the differentiation of CD44+MyD88+ ovarian CSC/TICs into cancer cells with mesenchymal features both in vitro and in vivo, confirming the importance of TWIST1 in the differentiation of ovarian CSC/TICs." (PMID 23528891, 2013). "Additionally, Twist1 is associated with cancer cell invasion and poor survival in HCC patients." (PMID 37495969, 2023). "Twist1 can facilitate carcinoma evolution through the cancer cell multiplication enhancement and apoptosis inhibition, leading to strengthened chemotherapy susceptibility of cancer cells and an extended colony of cancer stem cells to prompt the metastasis and invasiveness." (PMID 36213838, 2022). "Matched TWIST1-proficient versus TWIST1-deficient cells embedded into Matrigel plugs were injected subcutaneously to mice and the resulting plugs were harvested 14 days later and processed for IHC staining to analyze the degree of cancer cell infiltration and TWIST1 and CSF1 protein expression." (PMID 33466385, 2021). "As a consequence, the EMT associated transcription factors Twist1 and 2 may override oncogene-induced premature senescence in cancer cells, providing a link between early escape from failsafe programs/prevention of oncogene-induced senescence and the acquisition of invasive features by cancer cells." (PMID 21914164, 2011).
cancer (continued). "Germline mutations in CDH1 and TWIST1 may be associated with inherited cancer susceptibility." (PMID 19493342, 2009). "CNa 29 significantly reduced filamin A cleavage, vimentin expression, TWIST1 transcription, and the expressions of genes related to cancer stemness and increased the efficacy of doxorubicin, a chemotherapy drug commonly used for TNBC in clinical settings." (PMID 40151834, 2025). "Previous studies have reported that transcription factors, such as YAP/TAZ, NF-κB, β-catenin, and Twist1, were also localized in the nuclei of cancer cells on stiff substrates." (PMID 40124511, 2025). "TWIST1 was found to direct an embryonic developmental program for prostate organogenesis, thereby facilitating cancer metastasis." (PMID 40861808, 2025). "Over-expression of Twist1 was related to resistance to both conventional chemotherapy and target agents in many cancer cell types." (PMID 38415469, 2025). "Understanding the discrete functions of TWIST2 and TWIST1 is imperative in the advancement of therapies to eradicate drug resistance and to improve the outcomes in cancer." (PMID 39941895, 2025). "SPZ1 acts as a proto-oncogene and forms an SPZ1-TWIST1 complex through the acetylation of TWIST1 during tumorigenesis, which is essential for cancer cell migration." (PMID 41044669, 2025). "CNa 29, a calpain 2‐specific inhibitor, reduced cancer cell proliferation, decreased filamin A cleavage, downregulated TWIST1 expression, and significantly retarded metastasis." (PMID 40151834, 2025). "Taken together, these results indicate an important role of TWIST1 as a regulator of epithelial plasticity during cancer metastasis." (PMID 40869272, 2025). "In vitro experiments showed that upregulation of Twist1 in cancer cells activated CCL2 mRNA transcription; A chemotactic gradient is generated by the secretion of CCL2 protein to promote macrophage infiltration and subsequent angiogenesis stimulation." (PMID 41341593, 2025). "EMT, which plays an important role in cancer cell chemoresistance, is a complex process controlled by various transcriptional regulators such as Twist1, Snail, Slug and Zeb1." (PMID 40344465, 2025). "EMOGI successfully identified diverse genetic alterations in well-established cancer genes, including APC high mutation frequency in colon cancer, TWIST1 promoter hypermethylation, and MYC copy number amplifications across multiple cancer types." (PMID 40565540, 2025). "Twist1 up-regulation in cancer cells activates the transcription of CCL2 mRNA, thus promoting CCL2 expression." (PMID 41341593, 2025). "The EMT-associated transcription factor TWIST1 has been reported to be transcriptionally enabled by various cytokines (IL-6 or TGF-β), thereby triggering EMT in cancer cells." (PMID 40424038, 2025). "The transcription factor Twist1, belonging to the Twist family, which encodes a basic helix-loop-helix DNA-binding domain, is a key transcription factor that promotes EMT and cancer metastasis." (PMID 38590646, 2024). "Later on, Weinberg’s group revealed that TWIST1 plays an essential role in cancer metastasis via promoting EMT." (PMID 39164745, 2024). "This EMT system provides a robust model to investigate cancer metastasis-driving genes and their effects on Twist1-mediated EMT." (PMID 39648980, 2024). "Functional assays have shown that TWIST1 reversed the inhibitory effects of over-expressed TFPI-2 on cancer." (PMID 39153052, 2024). "TWIST1 is extensively expressed in cancer, and through controlling the TGF-β/SMAD3 signaling pathway, it promotes EMT and carcinogenesis." (PMID 38589525, 2024). "Methylation of CGIs in the TWIST1 promoter region has been identified in various cancers, such as gastric, breast, colorectal, and lung cancers." (PMID 38575639, 2024). "Studies have also found that exogenous overexpression of Twist1 increases the invasion and metastasis of cancer cells by promoting the down-regulation of E-cadherin and induction of EMT." (PMID 38835366, 2024).
cancer (continued). "We have also evaluated the levels of pleiotropic transcripts – TWIST-1 and WISP-1, both associated, i.a., with cancer cell development, viability, and metastasis." (PMID 38342891, 2024). "Twist1 is also a master regulator of EMT in cancer, and it is known to play a pivotal role in the acquisition of metastatic features and angiogenesis." (PMID 38473317, 2024). "Targeted Twist1 or Twist1 related molecules has been shown to be a promising cancer treatment method." (PMID 38191892, 2024). "Twist1 and Twist2, integral members of the bHLH transcription family, are fundamental to cancer proliferation." (PMID 38329598, 2024). "Twist1 is highly expressed in various cancers; it promotes tumor cell EMT and invasion by activating EMT-related target genes, such as Bmi1, ZEB2, and Snail, which enhance cell differentiation and migration rates." (PMID 38590646, 2024). "Targeting treatment of Twist1 or Twist1 related molecules has shown to be a promising cancer therapy method." (PMID 38191892, 2024). "Another pathway activated in the hypoxic environment is nuclear factor κ-light-chain-enhancer of activated B cell (NF-κB) signaling, which also contributes to EMT induction and invasive cancer cell phenotype maintenance via upregulating TWIST1 expression." (PMID 39201656, 2024). "Proteins such as Twist1, Snail, and MMP9 are implicated in the EMT, migration, and invasion of cancer." (PMID 39000112, 2024). "We found a correlation between PROM2 expression and the three EMT markers ZEB1, SNAI1 and TWIST1 in both cancer types." (PMID 38515278, 2024). "Twist1 plays multiple roles in cancer, affecting the occurrence, progression, and metastasis of tumors." (PMID 38191892, 2024). "Recently, Twist1 has been established to play pivotal roles not only in the development of various organs and systems but also in cancer metastasis." (PMID 38510272, 2024). "The decreased expression of the EMT-regulated protein Twist1 causes cancer cells to undergo EMT, which promotes tumor recurrence or reactivation by restoring the epithelial features of cancer cells." (PMID 38404689, 2024). "TWIST1 affects various biological processes that contribute to the initiation, progression, and metastasis of cancers." (PMID 38791037, 2024). "In accordance with the role of Twist1 in Endo-MT during cancer progression, Twist1 regulates mesenchymal phenotypes including the enhanced proliferation and migration in ECs during development and cardiovascular diseases." (PMID 38416830, 2024). "TWIST1 is a transcription factor that induces epithelial-mesenchymal transition (EMT) to promote cancer cell invasion, metastasis, stemness, and drug resistance when it is expressed in breast and other cancer cells." (PMID 38893094, 2024). "During this progression, TWIST1 also induced PD-L1 expression to enable the cancer cells to suppress immune clearance." (PMID 38893094, 2024). "An increase in Twist1 can indirectly inhibit cell cycle arrest and apoptosis and promote cancer metastasis." (PMID 38102691, 2023). "The regulation of Twist1 expression in cancer is a complicated process including modulation at many levels and depending on the cancer type and tissue context." (PMID 36900319, 2023). "Despite the research on the roles of Twist1 in embryonic development, cancer, and fibrotic diseases to date, it is essential to further explore how Twist1 regulates lipid and glucose metabolism." (PMID 37784111, 2023). "In this cancer, upregulation of Notch4 expression promotes metastasis through the regulation of Twist1 expression, which indicates a poor prognosis." (PMID 37108670, 2023). "TWIST1 promotes the invasion and metastasis of these cells as well as the phenotype of cancer stem cells, thus promoting drug resistance." (PMID 37115802, 2023). "Genes that regulate EMT such as Twist1, SOX9 and REX1 have been associated with an increased occurrence of EMT in cancer cells, leading to enhanced cell stemness, proliferation and metastasis." (PMID 36980876, 2023).
cancer (continued). "The TWIST1 and MYC genes are well-known and important regulators of cancer-associated processes and remain objects of active research in the field of oncology." (PMID 37298233, 2023). "KEGG enrichment analysis performed for the top 100 co-expressed genes with TWIST1 showed the co-expressed genes were involved in terms of pathways in cancer, focal adhesion, and Wnt signalling pathway." (PMID 37393249, 2023). "Studies on clinical samples have shown that high expression levels of Twist1 are highly correlated with cancer cell invasion and migration." (PMID 36732432, 2023). "We and our colleagues have published extensively on the use of TWIST1 siRNA delivered by nanoparticles to combat cancer." (PMID 38139368, 2023). "Tenascin-C is involved in phenotypic control of fibroblasts elsewhere—it acts with Twist1 transcription factor signalling to stably, but reversibly, activate fibroblasts in wound healing and permanently in fibrotic pathology and cancer." (PMID 36834965, 2023). "For example, multiple studies have reported that EMT drivers, such as SNAI2, ZEB1 and Twist1, play critical roles in cancer cell stemness in cancers." (PMID 36808651, 2023). "Some report also shows that Emodin can suppress the PTHLH expression in related cancer by suppressing the TCF4/TWIST1‐induced complex." (PMID 37555363, 2023). "Transwell assays revealed that fewer cancer cells migrated through the membrane in the TWIST1-knockdown group than in control." (PMID 37393249, 2023). "This has since led to the discovery of Twist1 as a key component in promoting metastasis in a number of other cancers." (PMID 36980876, 2023). "Several studies have demonstrated that the overexpression of Twist1 is upregulated in several cancer types including breast, liver, prostate, melanomas, and endometrial cancer." (PMID 37495969, 2023). "The glucose uptake is dramatically increased in cancer cells, and Twist1 is inextricably intertwined with glucose metabolism." (PMID 37784111, 2023). "In the majority of the 5 cancer types, PIK3CD expression was linked favorably with the expression of mesenchymal markers such as VIM (Vimentin), TWIST1, SNAI1 (SNAIL), SNAI2 (SLUG), and CDH2." (PMID 37861728, 2023). "They demonstrated that the effect of TWIST1 on E-cadherin is mediated through C3 and C3 decreased E-cadherin expression on cancer cells and promoted epithelial to mesenchymal transition." (PMID 37371512, 2023). "Twist1, a basic helix-loop-helix (bHLH) transcription factor, plays key regulatory roles in embryonic development, metabolic disease and cancer." (PMID 37996425, 2023). "In cancer cells, Twist1 suppresses E-cadherin and stimulates N-cadherin expression in a SNAIL-independent manner." (PMID 37444447, 2023). "The EMT core regulators ZEB1, ZEB2, Snail, Slug and TWIST1 are up-regulated in claudin-low cancers independently of the status of ER expression." (PMID 37504297, 2023). "Stiff ECMs activate transcription factors, such as nuclear factor-κB (NF-κB), twist family bHLH transcription factor 1 (Twist1), and yes-associated protein (YAP), thereby promoting malignant phenotypes in cancer cells." (PMID 36826318, 2023). "In the process of EMT transformation, up-regulated expression of transcription factors, such as Snail1, Twist1, Zeb1, and Zeb2, can increase the migration and invasion of cancer cells." (PMID 37115802, 2023). "Various reports in the research setting support our findings, as TWIST1 overexpression has been reported to be a chemoresistant factor in various cancers." (PMID 36764935, 2023). "TWIST1 and related factors are frequently tied to cancer cell stemness and changes in therapeutic responses and thus are now being viewed as attractive therapeutic targets." (PMID 38139368, 2023). "Since USP29 increases cancer cell migration and invasion through TWIST1 in vitro, we further investigated USP29 function in TNBC metastasis in vivo." (PMID 36782089, 2023).